GPAT4-AS1 (GPAT4 and GINS4 antisense RNA 1)
Synonyms: GIAT4RA
Gene: Long non-coding RNA gene on chromosome 8 (41,509,593 to 41,578,421, reverse strand). Ensembl gene ENSG00000253133.
Diseases named in the same sentence as GPAT4-AS1 in open-access papers:
GPAT4-AS1 is named in the same sentence as 2 diseases in open-access papers, as found by Europe PMC text mining. Sharing a sentence is not in itself a finding about the gene and the disease.
GPAT4-AS1 shares sentences with these, for which no sentence is quoted: tumor (2 papers); lung carcinoma (1).